RNU6-415P (RNA, U6 small nuclear 415, pseudogene)
Gene: Small nuclear RNA gene on chromosome 15 (78,898,840 to 78,898,936, reverse strand). Ensembl gene ENSG00000252061.
Homologues: Orthologues: chimpanzee U6 (97% identical), macaque U6 (94% identical), guinea pig U6 (75% identical), pig U6 (70% identical). Paralogues in human: RNU6-737P (81% identical), RNU6-1011P (80% identical), RNU6-1164P (80% identical), RNU6-28P (80% identical), RNU6-73P (80% identical), RNU6-12P (79% identical), RNU6-13P (79% identical), RNU6-207P (79% identical), RNU6-31P (79% identical), RNU6-32P (79% identical), RNU6-809P (79% identical), RNU6-1 (78% identical), and 1285 more.